ETS1 (ETS proto-oncogene 1, transcription factor)
Diseases named in the same sentence as ETS1 in open-access papers (continued):
Sharing a sentence is not in itself a finding about the gene and the disease.
thyroid cancer (4 papers, 2014 to 2025). "Our research proved that AFAP-AS1 could facilitate progression of thyroid cancer sponging miR-155-5p through ETS1/ERK pathway." (PMID 33999777, 2021). "Conversely, factors such as ETS1 and ETV5 showed high and consistent expression across thyroid cancer types, whereas most ETS proteins, including GABPA, were expressed at intermediate levels." (PMID 35053525, 2022). "Bioinformatic predictions indicate that miR-203a-3p and miR-204-3p share a seed sequence with the 3’UTR of ETS1 mRNA, but there have been no studies on mutual expression of ETS1 and miR-203a-3p/204-3p in thyroid carcinomas." (PMID 39941022, 2025).
type 2 diabetes (4 papers, 2009 to 2024). "Increased ETS1 expression is associated with β-cell dysfunction induced by glucotoxicity in type 2 diabetes." (PMID 32527043, 2020). "Our study now provides evidence that in vivo and in vitro the number of VPC is reduced in conditions of type 2 diabetes and that one major signalling pathway involved is the activation of the transcription factors ETS1 and ETS2." (PMID 19225563, 2009). "Since TXNIP was found to be induced in β-cells in human type 2 diabetes, it will be interesting to determine whether phosphorylation of Ets1 is induced as well." (PMID 24897113, 2014). "To demonstrate a causal link between ETS transcription factors and the reduced number of progenitor cells in type 2 diabetes, we transfected peripheral blood-derived mononuclear cells with control siRNA or siRNA against ETS1 and incubated them with high glucose for 3 days." (PMID 19225563, 2009).
viral infection (4 papers, 2019 to 2025). "In addition, some of the genes involved in endothelial cell migration (ETS1, LGALS8, and PDCD10) are also known to be associated with perturbations during viral infection." (PMID 33240937, 2020). "ETS1 is the prototype of the ETS family of transcription activators and plays an important role in host transcriptional response and in regulation of immune cell function, T cell activation and cytokine expression, and viral infection." (PMID 40198713, 2025).
autoimmune thyroiditis (3 papers, 2021 to 2025). "We found that the ETS1 co-expressed genes were positively enriched in the immune-related pathways, including primary immunodeficiency, autoimmune thyroid disease, Th1 and Th2 cell differentiation, chemokine signaling pathway, etc.." (PMID 34686186, 2021). "We confirmed that miR-326 contributes to autoimmune thyroiditis by targeting Ets-1 protein to regulate Th17/Treg balance in autoimmune thyroiditis, and tail vein injection may achieve a better intervention effect." (PMID 34140947, 2021).
cardiac hypertrophy (3 papers, 2012 to 2025). "For example, the ETS transcription factor Ets1 has been shown to mediate angiotensin II-related cardiac fibrosis and cardiac hypertrophy, while increased ETV1 activity has been shown to induce atrial remodeling and arrhythmia." (PMID 35236346, 2022). "Increasing evidence has demonstrated that Ang II, via its type 1 receptor, activates a number of signaling pathways, including ROS, and transcriptional factors such as NF-κB, Ets-1, and early growth response 1 to regulate cardiac hypertrophy, inflammation, and fibrosis." (PMID 22558139, 2012). "Additionally, in an experimental mouse model with autoimmune myocarditis, treatment with spironolactone (an aldosterone receptor antagonist) significantly alleviated myocardial hypertrophy, improved cardiac function, and diminished myocardial fibrosis via inhibition of ETS1." (PMID 40870883, 2025).
Cerebral ischemia (3 papers, 2018 to 2025). Restriction of arterial blood supply to the brain associated with insufficient oxygenation to support the metabolic requirements of the tissue. "CASC15 promotes cerebral ischemia/reperfusion injury via miR-338-3p/ETS1 axis in acute IS64." (PMID 38653998, 2024). "Specifically, integrin α5β1 regulates cerebral ischemia-induced BEC activation of Tie2 and priming of BECs with Ang1 via the Tie2/Ets-1 pathway, significantly upregulating the expression of integrin α5." (PMID 30185785, 2018).
colon adenocarcinoma (3 papers, 2002 to 2025). "A correlation was observed between the expression of PTPN1 and ETS1 in colon adenocarcinoma samples." (PMID 40356520, 2025).
COVID-19 (3 papers, 2021 to 2023). A disease caused by infection with severe acute respiratory syndrome coronavirus 2. "To assess the informativeness of MCEMP1, ETS1 and HLA-DRA throughout each phase of COVID-19, we examined the temporal dynamics of these transcripts before and after the nadir of respiratory function from the same study cohort." (PMID 36801619, 2023). "On the other hand, ETS1 and HLA-DRA, were differentially downregulated by 2.10 fold and 2.28 fold, respectively, in severe COVID-19 patients." (PMID 36801619, 2023). "The most consistent differentially regulated genes in peripheral blood of severe COVID-19 patients were MCEMP1, HLA-DRA and ETS1 across the 7 transcriptomics datasets." (PMID 36801619, 2023). "The comparative transcriptomics analysis indicated MCEMP1, ETS1 and HLA-DRA as the most promising candidates in discriminating severe vs mild COVID-19 outcomes." (PMID 36801619, 2023). "We used a total of 7 publicly available RNAseq datasets, comprising of a total of 140 severe and 181 mild COVID-19 patients collected during the acute phase of SARS-CoV-2 infection, and uncovered that the top differential genes included MCEMP1, ETS-1 and HLA-DRA." (PMID 36801619, 2023). "Since severe COVID-19 is characterised by increased C Reactive Protein (CRP) and lymphopenia, which were used in several COVID-19 clinical severity scores, we correlated the abundance of MCEMP1, ETS1 and HLA-DRA transcripts to CRP and lymphocyte counts." (PMID 36801619, 2023).
endometrial carcinoma (3 papers, 2018 to 2021). A malignant tumor arising from the epithelium that lines the cavity of the uterine body. "Curcumin has been shown to promote cell apoptosis by downregulating Ets-1 and Bcl-2 in endometrial carcinoma." (PMID 32083122, 2019). "Moreover, the GSK3β inhibitor LY2090314 – which has already undergone clinical testing – induced ETS1 degradation in ovarian and endometrial cancer cells, an effect blocked by MG132 in the presence of GSK3β siRNA." (PMID 34023818, 2021).
gastric tumor (3 papers, 2016 to 2025). "The expression difference of the reporter gene suggests that the CRISPReader system can effectively distinguish gastric tumor cells from normal gastric cells, indicating that the Ets-1-sensing CRISPReader system has potential broad-spectrum anti-tumor capabilities." (PMID 34124154, 2021).
gastritis (3 papers, 2020 to 2025). Inflammation of the stomach. "In a recent study of Helicobacter pylori-associated gastritis, ETS1 expression was shown to be induced by infection and to activate proinflammatory gene expression." (PMID 40198713, 2025). "Collectively, these data showed that ETS1 may play an important role in the pathogenesis of H. pylori-associated gastritis." (PMID 32612120, 2020). "Notably, these findings reveal that ETS1 may play a crucial role in the pathogenesis of H. pylori-associated gastritis." (PMID 32612120, 2020). "The levels of ETS1 expression was significantly correlated with the severity of gastritis." (PMID 32612120, 2020).
head and neck cancer (3 papers, 2019 to 2025). A primary or metastatic malignant neoplasm affecting the head and neck. "To confirm the results from culture cells, we wanted to examine if ETS-1 expression in cisplatin-resistant head and neck cancer tissue is higher than that in cisplatin-sensitive tissues." (PMID 31118072, 2019). "The overexpression of ETS-1 in cisplatin-resistant head and neck cancer cell lines (Cal27 and Fadu) led to reduced apoptosis and promoted rapid cellular invasion and survival of these head and neck cancer cells." (PMID 38201459, 2023). "Among them, 6 genes were highly expressed in head and neck cancers, namely SLC1A5, ETS1, NDRG1, RHEB, HIF1A and CDH2." (PMID 41317550, 2025).
Hypertension (3 papers, 2018 to 2025). The presence of chronic increased pressure in the systemic arterial system. "Elevated serum levels of ETS1 and ITPR3 could be used in routine screening for high‐risk individuals, such as the elderly or those with hypertension, smoking or a family history of AAA." (PMID 39823264, 2025). "In summary, ETS-1 plays a major role in the development of vascular and renal injury and is a potential target for the development of novel therapeutic strategies to ameliorate end-organ injury in hypertension." (PMID 29970819, 2018).
Immunodeficiency (3 papers, 2021 to 2025). Failure of the immune system to protect the body adequately from infection, due to the absence or insufficiency of some component process or substance. "The deletion of the FLI-1, ETS1, JAM3 and THYN1 genes was considered to be directly associated with the immunodeficiency exhibited by the patient." (PMID 34440371, 2021). "Genetically, FLI1 and ETS1 are seen as causative for the immunodeficiency, but these genes were deleted nor duplicated in 4 of our 14 patients." (PMID 35763218, 2022). "The expression of the THYN1 gene in these immune cells leads us to propose its implication in the immunodeficiency of JBS patients, along with FLI-1, ETS1, NFRKB and JAM3." (PMID 34440371, 2021). "ETS1, NFRKB, JAM3 and THYN1 genes could also play a role in the presence of immunodeficiency." (PMID 34440371, 2021). "ETS1 and FLI1 involvement did not correlate to patients with immunodeficiency of B nor T lymphocyte dysfunction in our cohort." (PMID 35763218, 2022).
ischemic stroke (3 papers, 2018 to 2025). A stroke disorder caused by obstruction of blood flow to the brain, due to thrombotic (local blood clot formation) or embolic (due to a blood clot or other material traveling from another site) event. "Studies are underway to understand the mechanisms by which ETS-1 is regulated following ischemic stroke and how it is affected by NRG1." (PMID 29856744, 2018). "Downregulation of miR-145 in adipose-derived stem cells could promote its differentiation toward endothelial cells through the expression of ETS1 (V-ets avian erythroblastosis virus E26 oncogene homolog 1) in ischemic stroke." (PMID 38743209, 2024).
malignant glioma (3 papers, 2020 to 2022). A grade III or grade IV glioma arising from the central nervous system. "The molecular mechanisms underlying MYBL2 and ETS1 overexpression in malignant gliomas are to date unknown." (PMID 35228525, 2022). "Of note, the expression of these transcription factors was independent of the IDH mutation status in malignant gliomas, except for ETS1." (PMID 35228525, 2022). "Given that we found EIF4EBP1 to be a target gene of the ETS1 and MYBL2 oncoproteins in malignant gliomas, 4EBP1 may possibly contribute to ETS1 and MYBL2 tumorigenic functions in these tumors." (PMID 35228525, 2022). "Finally, by employing transient knock-down experiments to repress either of these transcription factors, we identified MYBL2 and ETS1 as the relevant transcriptional drivers of enhanced EIF4EBP1 expression in malignant glioma cells." (PMID 35228525, 2022). "ETS1 upregulates the expression of the integrin α5 subunit and mediates intracellular signal transduction and invasion processes, leading to the occurrence of malignant glioma." (PMID 34863158, 2021).
periodontitis (3 papers, 2019 to 2023). An acute or chronic inflammatory process that affects the tissues that surround and support the teeth. "In contrast, 8 MRs (ESR1, CEBPB, FOS, BCL6, E2F1, SPI1, STAT3, and ETS1) were consistently expressed at higher levels (U test statistic between 10 and 16) in the periodontitis condition." (PMID 37834287, 2023). "Three functional modules have been revealed and top TFs such as EGR1 and ETS1 have been shown to regulate the expression of periodontitis-related immune genes that play an important role in the formation of the immunosuppressive microenvironment." (PMID 33841510, 2021). "Within this group, both EGR1 and ETS1 played a key role in regulating the expression of crucial immune genes and forming the immunosuppressive microenvironment observed during the pathogenesis of periodontitis." (PMID 37834287, 2023). "The TFs involved are the two high-outdegree TFs, ETS1 and EGR1, which reveals that the TFs ETS1 and EGR1 play a crucial role in the invasion and activity of immune cells in periodontitis." (PMID 33841510, 2021). "In addition to ETS1, our analyses also identified EGR1 (Early Growth Response 1) as MR in periodontitis." (PMID 37834287, 2023).
schizophrenia (3 papers, 2023 to 2025). A major psychotic disorder characterized by abnormalities in the perception or expression of reality. "Similarly, both transcriptome and GWAS data have demonstrated the ETS1 expression alterations in schizophrenia patients." (PMID 37494308, 2023). "Certain TFs such as ETS1, MAF, SMARCA2, TRPS1, and CREB3L1 appear to modulate TF-tagged genes in multiple traits, which could be key elements linking AD, bipolar disorder, and schizophrenia through shared regulatory pathways." (PMID 39905509, 2025).
uveitis (3 papers, 2014 to 2025). An inflammatory process affecting a part of or the entire uvea. "This study aimed to investigate the association of miR-146a and Ets-1 gene polymorphisms with pediatric uveitis in a Han Chinese population." (PMID 24658012, 2014). "We also identified an association between SNP rs10893872 of Ets-1 and pediatric uveitis in the present study." (PMID 24658012, 2014). "In conclusion, our study has identified the associations of rs2910164 (miR-146a) and rs10893872 (Ets-1) with pediatric uveitis." (PMID 24658012, 2014). "Concerning the important roles of Ets-1, the increased frequency of the rs10893872 CC genotype in patients and the increased expression of Ets-1 in CC genotype carriers suggest that Ets-1 is a predisposing factor in pediatric uveitis." (PMID 24658012, 2014). "We showed a significant association between both miR-146a and Ets-1 gene polymorphisms and pediatric uveitis in our study population." (PMID 24658012, 2014). "It was found that rs2910164 of miR-146a and rs10893872 of Ets-1 were both associated with pediatric uveitis." (PMID 24658012, 2014). "Because a significant association was found between SNP rs10893872 and pediatric uveitis patients, we further tested the expression of Ets-1 in PBMCs obtained from 32 healthy individuals with a known genotype for this SNP." (PMID 24658012, 2014). "Frequencies of genotypes and alleles of microRNA (miR)-146a and Ets-1 polymorphisms in pediatric uveitis patients and controls." (PMID 24658012, 2014). "This study shows that miR-146a and Ets-1 are both associated with pediatric uveitis in Han Chinese." (PMID 24658012, 2014). "SNP rs10893872 may affect the genetic predisposition to pediatric uveitis by modulating expression of Ets-1." (PMID 24658012, 2014). "A total of 5 SNPs of miR-146a and Ets-1 were successfully genotyped in 520 pediatric uveitis patients and 1204 normal controls." (PMID 24658012, 2014). "In the present study, we investigated the association of five SNPs of miR-146a and the transcription factor Ets-1 with pediatric uveitis patients in a Chinese Han population." (PMID 24658012, 2014). "We have not investigated whether the SNP rs10893872 influencing Ets-1 expression can also affect the production of cytokines importantly involved in pediatric uveitis development." (PMID 24658012, 2014).
acute kidney injury (2 papers, 2018 to 2022). Sudden and sustained deterioration of the kidney function characterized by decreased glomerular filtration rate, increased serum creatinine or oliguria. "In a model of acute renal failure, the tubular expression of ETS-1 is increased and associated with increased expression of cyclin D, suggesting that ETS-1 participates in the control of tubular regeneration in acute renal failure." (PMID 29970819, 2018).
Alzheimer disease (2 papers, 2014 to 2025). A progressive, neurodegenerative disease characterized by loss of function and death of nerve cells in several areas of the brain leading to loss of cognitive function such as memory and language. "As an angiogenic transcription factor, ETS1 has recently been identified as a biomarker for the diagnosis of Alzheimer's disease (AD)." (PMID 39823264, 2025).
anaplastic thyroid cancer (2 papers, 2021 to 2022). "LncRNA AFAP-AS1 promotes anaplastic thyroid cancer progression by sponging miR-155-5p through ETS1/ERK pathway." (PMID 35264071, 2022). "Next, we proved that ETS1 took an important part in the progression of anaplastic thyroid cancer by controlling Erk phosphorylation." (PMID 33999777, 2021). "Compared to previous study, we initially demonstrated that depletion of AFAP-AS1 inhibited progression of anaplastic thyroid cancer through miR-155-5p/ETS1/Erk pathway." (PMID 33999777, 2021). "Subsequently, a series of bioinformatic technologies and molecular experiments indicated that lncRNA AFAP-AS1 exerted its oncogene function through miR-155-5p/ETS1/Erk axis in anaplastic thyroid cancer." (PMID 33999777, 2021). "Thus, AFAP-AS1/miR-155-5p/ETS1/Erk axis was demonstrated to influence the progression of anaplastic thyroid cancer." (PMID 33999777, 2021).
bronchopulmonary dysplasia (2 papers, 2023 to 2024). Bronchopulmonary dysplasia is a chronic respiratory disease that results from complications related to lung injury during the treatment of infant acute respiratory distress syndrome in low-birth-weight premature infants or from abnormal lung development in older infants. "ETS1 plays a protective role in bronchopulmonary dysplasia (BPD) by inhibiting oxidative stress-induced ferroptosis." (PMID 39102510, 2024).
depression (2 papers, 2024 to 2025). "Five of these TFs, namely ETS1, TFAP2A, NFKB2, CTCF, and RELA, are significantly deregulated in the blood samples of depression patients compared to controls (GSE217811 and GSE23848)." (PMID 38256187, 2024).
diffuse large B-cell lymphoma (2 papers, 2020 to 2025). "In diffuse large B-cell lymphoma (DLBCL), ETS1 modulates B-cell signaling, differentiation, and immune-related genes, with FCMR identified as a novel target that promotes lymphomagenesis." (PMID 40181983, 2025).
dysplasia (2 papers, 2016 to 2023). A usually neoplastic transformation of the cell, associated with altered architectural tissue patterns. "The target genes of many miRNAs can express transcription factors and are associated with cardiac dysplasia and apoptosis, such as Nkx2.5, Zeb2, Mef2c, and Ets1." (PMID 38053046, 2023). "In addition, the ETS-1 expression increased gradually from adjacent normal tissues, mild to moderate dysplasia tissues and severe dysplasia tissues, suggesting that it is associated with the occurrence and progression of LSCC." (PMID 26826553, 2016).
endothelial dysfunction (2 papers, 2021 to 2025). In vascular diseases, endothelial dysfunction is a systemic pathological state of the endothelium (the inner lining of blood vessels) and can be broadly defined as an imbalance between vasodilating and vasoconstricting substances produced by (or acting on) the endothelium. "The understanding of the miR-200a-3p/Ets-1/PIGF/VEGF-A axis provides new insights in the endothelial dysfunction mechanisms involved during cardiac fibrosis." (PMID 33969024, 2021).
epilepsy (2 papers, 2021 to 2025). A brain disorder characterized by episodes of abnormally increased neuronal discharge resulting in transient episodes of sensory or motor neurological dysfunction, or psychic dysfunction. "It should be noted, however, that the ETS expression profile is also different in epilepsy; ELF1, ELK1, ELK4, ETS1, ETS2, and ETV1 are expressed at higher levels than ELF4, ELK3, and ETV4, and there is also variability in expression among different types of epilepsy." (PMID 33671331, 2021).